FOSL1 (FOS like 1, AP-1 transcription factor subunit)
Diseases named in the same sentence as FOSL1 in open-access papers (continued):
Sharing a sentence is not in itself a finding about the gene and the disease.
head and neck cancer (3 papers, 2022 to 2025). A primary or metastatic malignant neoplasm affecting the head and neck. "Previously, we showed that FOSL1 promoted EMT by activating SNAI2 expression in a superenhancer-dependent manner in head and neck cancer, indicating that FOSL1 is a master regulator of EMT-related transcription factors." (PMID 36185257, 2022). "This is also supported by our finding that FOSL1 (FRA1), a subunit of the transcription factor AP-1 and a known driver of metastasis in head and neck cancer, is upregulated in RARGKO cells and contains RARγ peaks within its regulatory regions in PAR cells." (PMID 41274504, 2025).
lymph node metastasis (3 papers, 2022 to 2023). "Furthermore, increased nuclear FOSL1 expression was correlated with lymph node metastasis." (PMID 37642779, 2023). "In consistent with above findings, we also found that low GATA3 mRNA predicted poor DMFS for patients with or without lymph node metastasis and that high FOSL1 predicted a poor outcome for patients with no lymph node metastasis." (PMID 37353480, 2023).
malignant glioma (3 papers, 2010 to 2023). A grade III or grade IV glioma arising from the central nervous system. "In malignant gliomas, thyroid, and some other tumors, higher FOSL1 levels are associated with the development of a malignant phenotype." (PMID 35163444, 2022). "In summary, FOSL1 overexpression is characteristic for the most aggressive forms of cancer, such as TNBC and malignant glioma." (PMID 35163444, 2022). "In addition, one of the most aggressive forms of cancer, malignant glioma, is also characterized by high AP1 transcriptional activity and, particularly, by higher levels of FOSL1." (PMID 35163444, 2022).
ulcerative colitis (3 papers, 2018 to 2023). An inflammatory bowel disease involving the mucosal surface of the large intestine and rectum. "In addition, oxidative stress in inflamed intestinal biopsies induced FOSL1 gene expression, thereby promoting the expression of IL11 in ulcerative colitis patients." (PMID 37153732, 2023).
autoimmune disease (2 papers, 2017 to 2022). A disorder resulting from loss of function or tissue destruction of an organ or multiple organs, arising from humoral or cellular immune responses of the individual to their own tissue constituents. "We identified hundreds of autoimmune disease-associated SNPs within the genomic-binding sites of FOSL1, FOSL2 and BATF." (PMID 35511484, 2022). "Our study further reveals that the genomic binding sites of FOSL1, FOSL2 and BATF harbour hundreds of autoimmune disease-linked SNPs." (PMID 35511484, 2022).
bile duct cancer (2 papers, 2021 to 2025). "FOSL1, a transcription factor, has been shown in previous studies to be highly upregulated in bile duct cancer in both humans and mice, correlating with poorer survival outcomes." (PMID 39944827, 2025).
clear cell renal cell carcinoma (2 papers, 2025). "Additionally, ETV4 binds to the FOSL1 promoter, relying on PI3K-AKT signaling to directly upregulate FOSL1, leading to metastasis and disease progression in clear cell renal cell carcinoma." (PMID 40469297, 2025).
endometrial carcinoma (2 papers, 2006 to 2019). A malignant tumor arising from the epithelium that lines the cavity of the uterine body. "Herein, we demonstrated that knockdown of PGK1 inhibited the expression of c-JUN, FOSL1, and POLD1, indicating that PGK1 regulates chemoresistance in endometrial carcinoma through upregulation of DNA repair-related proteins." (PMID 30925862, 2019).
epilepsy (2 papers, 2021 to 2022). A brain disorder characterized by episodes of abnormally increased neuronal discharge resulting in transient episodes of sensory or motor neurological dysfunction, or psychic dysfunction. "In the post-brain-insult epilepsy model generated by PILO-induced SE, the expression of FosL1 mRNA increased 3 h after SE and was maintained at a higher level than in naïve mice at 2 and 7 days after SE." (PMID 34681621, 2021).
fibroma (2 papers, 2023 to 2024). A non-metastasizing neoplasm arising from the fibrous tissue. "To explore the specificity of these findings in FOS and FOSL1 for desmoplastic fibroblastoma, we examined 15 fibroma of tendon sheath tumours, their principal histological mimic." (PMID 36426824, 2023). "Our investigation revealed that a majority of desmoplastic fibroblastomas harbour rearrangements in FOSL1 that distinguish them from their main mimic, fibroma of tendon sheath." (PMID 36426824, 2023). "Together, these findings indicated that FOSL1 rearrangements, detectable by immunohistochemistry or direct sequencing of the FOSL1 transcript, are a common feature in desmoplastic fibroblastoma and absent from fibroma of tendon sheath, including USP6 wild‐type cases." (PMID 36426824, 2023). "No fibromas showed strong uniform FOSL1 positivity, as observed in desmoplastic fibroblastoma." (PMID 36426824, 2023).
follicular thyroid carcinoma (2 papers, 2025). "Furthermore, research has shown that PMAIP1 influences the development of follicular thyroid carcinoma through the Wnt3/FOSL1 signaling pathway." (PMID 41323776, 2025).
Hypertension (2 papers, 2024). The presence of chronic increased pressure in the systemic arterial system. "To explore this, we compared the expression of hypertension-related genes including AVP, AT1R, and FOSL1, along with the oxidative stress marker mtROS, in the PVN between SPS and control rats." (PMID 39594564, 2024).
invasive breast carcinoma (2 papers, 2011 to 2023). A carcinoma that infiltrates the breast parenchyma. "According to the same dataset (Breast Invasive Carcinoma, TCGA PanCancer Atlas, 1082 samples), ITGB4, previously characterized as a negative prognosticator associated with the basal-like subtype, is the beta-family integrin best correlating with FOSL1 expression level." (PMID 37176013, 2023). "In the present review, we will focus on the functional roles, transcriptional mechanisms, and clinical significance of FOSL1/FRA-1 in the control of EMT and metastasis in invasive breast cancer." (PMID 37176013, 2023). "Therefore, in addition to being posttranscriptionally regulated by RBPs (IGF2BP1) interacting with the FOSL1 transcript, FRA-1 also cooperates with other RBPs, such as the RNA helicase DDX5, in invasive breast cancer." (PMID 37176013, 2023).
Knee Osteoarthritis (2 papers, 2023 to 2024). "This study recommended that for better outcomes in knee osteoarthritis, cultured ADSC-induced therapy should be supplemented with upregulation of FOSL1 expression." (PMID 38255196, 2024).
meningioma (2 papers, 2020 to 2021). A generally slow growing tumor attached to the dura mater. "The results showed yellow modules are negatively related to the degree of infiltration of resting mast cells in meningioma tissues, thus, genes such as MYC, CXCL2, CXCL8 and FOSL1 in the module, are inversely associated with the degree of mast cell infiltration." (PMID 34772393, 2021).
metastatic melanoma (2 papers, 2025). A melanoma that has spread from its primary site to another anatomic site. "FOSL1 expression levels are generally elevated in patients with metastatic melanoma." (PMID 41383633, 2025).
Obesity (2 papers, 2014 to 2023). Accumulation of substantial excess body fat. "Whether the presence or absence of obesity alters the properties of SF and the expression of FOSL1 requires further investigation." (PMID 36672268, 2023).
osteoarthritis (2 papers, 2021 to 2023). A noninflammatory degenerative joint disease occurring chiefly in older persons, characterized by degeneration of the articular cartilage, hypertrophy of bone at the margins and changes in the synovial membrane. "Therefore, the increase of FOSL1 in ADSCs using SF treatment may suppress osteoarthritis progression and reduce pain by inhibiting cartilage damage through the suppression of inflammatory cytokine production by ADSCs." (PMID 36672268, 2023).
pilocytic astrocytoma (2 papers, 2016 to 2022). Pilocytic astrocytoma is a rare subtype of low-grade glioma of the central nervous system characterized by a well circumscribed, often cystic, brain tumor with a discrete mural nodule and long, hair-like projections that extend from the neoplastic astrocytes. "The AP-1 transcription factor was predicted to bind within 200 bp of a subset of the 315 differentially methylated CpG sites; the AP-1 factors, FOS and FOSL1 were found to be up-regulated in pilocytic astrocytomas." (PMID 27229157, 2016). "The AP-1 transcription factors FOS and FOSL1 were found to be significantly up-regulated in the pilocytic astrocytomas compared to diffuse astrocytomas and normal brain controls." (PMID 27229157, 2016).
skin cancer (2 papers, 2011 to 2022). "MRNA levels of KLK6, LCN2 and FOSL1 were found to be significantly overexpressed in UV-induced skin tumours in K14-HPV8-CER mice compared to FVB/N wild-type skin, collected 24d after irradiation." (PMID 35406439, 2022). "Since the KEGG pathway analysis of DEGs of K14-HPV8-CER skin tumours also suggest an enrichment of genes regulating IL-17 signalling comprising LCN2 and FOSL1, this strongly points to an important role of IL-17 signalling in HPV8-mediated tumorigenesis." (PMID 35406439, 2022).
status epilepticus (2 papers, 2021 to 2022). Status epilepticus is defined as a continuous seizure lasting more than 30 min, or two or more seizures without full recovery of consciousness between any of them. "Pilocarpine-induced status epilepticus increased hippocampus FosL1 expression, along with inflammation." (PMID 34681621, 2021).
Alzheimer disease (1 paper, 2022). A progressive, neurodegenerative disease characterized by loss of function and death of nerve cells in several areas of the brain leading to loss of cognitive function such as memory and language. "The expression of transcription factors in each module had a substantial positive connection, and FOSL1, HES4, and MAFB identified the genes in the M4 module as a possible cluster of transcriptional regulators linked to the start of Alzheimer’s disease." (PMID 35592698, 2022).
ameloblastoma (1 paper, 2022). The most common odontogenic tumor, arising from the epithelial component of the embryonic tooth and usually affecting the molar-ramus region of the mandible or maxilla. "However, the impact of FOSL1 in ameloblastoma (AM) has not been clarified." (PMID 36185257, 2022).
aneurysm (1 paper, 2022). Bulging or ballooning in an area of an artery secondary to arterial wall weakening. "Of interest, increased expression of multiple genes in Tsc2 deficient macrophages including Mmp9, Fosl1, Fos and TSP-1 were involved as the downstream targets of CREB and associated with aneurysms formation." (PMID 36400753, 2022).
Anxiety (1 paper, 2015). Intense feelings of nervousness, tension, or panic often arise in response to interpersonal stresses. "FOSL1 has been previously associated with addiction, depression, and anxiety." (PMID 25880836, 2015).
bipolar disorder (1 paper, 2025). A disorder of the brain that causes unusual shifts in mood, energy, activity levels and the ability to carry out day-to-day tasks. "Our study finds that patients with bipolar disorder have higher levels of AP-1 transcription factor subunits (Jun, Fosb, Fosl1)." (PMID 40539026, 2025).
corneal disease (1 paper, 2023). "FOSL1, along with FOSL2, a novel candidate for corneal disease in our study, and other TFs from the FOS and JUN families, are known to be important in epidermal cells." (PMID 37856539, 2023).
cyst (1 paper, 2025). A sac-like closed membranous structure that may be empty or contain fluid or amorphous material. "To explore the molecular mechanism of cyst formation induced by the abnormal activity of IL-6/JAK/STAT3 signaling pathway, we focused on FOSL1, a target gene of the IL-6/JAK/STAT3 signaling pathway, whose gene expression was greatly increased in xCEP290 morphant kidney in our RNA-seq analysis." (PMID 40570958, 2025). "While FOSL1 is known to play an important role in various biological processes, its involvement in cyst formation has not been reported." (PMID 40570958, 2025).
embryonal carcinoma (1 paper, 2021). A non-seminomatous malignant germ cell tumor characterized by the presence of large germ cells with abundant cytoplasm resembling epithelial cells, geographic necrosis, high mitotic activity, and pseudoglandular and pseudopapillary structures formation. "We first analyzed expression levels of the four TFs after FOSL1 overexpression in a pluripotent human embryonal carcinoma cell line (NTERA-2) and in a human embryonic kidney 293 cell line (HEK-293T) selected due to low FOSL1 expression levels and discrete levels of the other four TFs." (PMID 34282187, 2021).
emphysema (1 paper, 2006). "Fifteen genes were thus found to be upregulated in fibroblasts of emphysema, among them IGFBP-rP1 (4.9-fold), LOX (3.3-fold), LOXL2 (3.9-fold) and TIMP3 (3.0-fold), whereas 121 genes were downregulated, among them CDK4 (6.3-fold), FOSL1 (4.8-fold), OAZ1 (6.7-fold) and IGFBP-5 (5.3-fold)." (PMID 16504044, 2006).
esophageal adenocarcinoma (1 paper, 2023). A malignant tumor with glandular differentiation arising predominantly from Barrett mucosa in the lower third of the esophagus. "Using binding motif analysis within these DMRs, we show that a cell-type-specific transcription factor HNF4A maintains the binding sites that it generates in normal cells, while establishing new binding sites cooperatively with novel partners such as FOSL1 in esophageal adenocarcinoma." (PMID 37620896, 2023).
fibrous tumours (1 paper, 2023). "The rare fibrous tumour desmoplastic fibroblastoma is characterised by overexpression of FOSL1." (PMID 36426824, 2023).
focal glomerular sclerosis (1 paper, 2019). "FOSL1 and FOSL2 are also members of the FOS gene family and overexpressed in various renal diseases like IgAN, lupus nephropathy, and focal glomerular sclerosis, with pivotal roles in glomerular sclerosis and mesangial proliferation." (PMID 31392215, 2019).
hypopharyngeal carcinoma (1 paper, 2025). Carcinoma, predominantly squamous cell, arising from the epithelial cells of the hypopharynx. "The journal retracts the article “HOXA11-AS1 promotes PD-L1–mediated immune escape and metastasis of hypopharyngeal carcinoma by facilitating PTBP1 and FOSL1 association”, cited above." (PMID 40488559, 2025).
infertile (1 paper, 2026). "Notably, reduced FOSL1 expression in infertile patients has been linked to dysregulated IL-17 signaling, underscoring its critical role in immune-structural coordination within the endometrium." (PMID 41514467, 2026).
inflammatory bone diseases (1 paper, 2025). "In addition, SCSP modulates inflammatory cascades by attenuating IL-17 signaling, Toll-like receptor pathways, and key genes implicated in inflammatory bone diseases, such as Ccl2, Il17re, Fosl1, Mmp13, Ccl5, Tlr1, Il12b, and Atp6v1b1." (PMID 40926992, 2025).
injury (1 paper, 2023). Damage inflicted on the body as the direct or indirect result of an external force, with or without disruption of structural continuity. "For example, studies have shown that FOSL1-deficient animals have less lung injury and a higher survival rate than the control group in experimental models of acute lung injury." (PMID 37405258, 2023).
ischemia (1 paper, 2023). A hypoperfusion of the BLOOD through an organ or tissue caused by a PATHOLOGIC CONSTRICTION or obstruction of its BLOOD VESSELS, or an absence of BLOOD CIRCULATION. "It was suggested that Fosl1 was upregulated and enriched in ischemic regions after acute ischemia in the ST." (PMID 38082331, 2023).
keratoconus (1 paper, 2023). A degenerative, structural disorder of the eye, characterized by a cone-shaped protrusion of the cornea. "This is in line with the reported link between keratoconus and down-regulation of FOSL1, an AP1 complex partner of FOSL2." (PMID 37856539, 2023).
large cell carcinoma (1 paper, 2017). A malignant epithelial neoplasm composed of large, atypical cells. "Moreover, the effect of FOSL1 inhibition was extended to mutant RAS cells from large cell carcinoma." (PMID 28220783, 2017).
lentivirus infection (1 paper, 2023). Virus diseases caused by the Lentivirus genus. "EdU proliferation assay showed that FOSL1-overexpressing lentivirus infection recovered the relative proliferation rate from about 57.19% of the control group in the EPHB2 siRNA transfected group to about 80.69%." (PMID 37949219, 2023). "Transwell migration assay demonstrated that EPHB2 siRNA-suppressed Schwann cell migration was rescued by FOSL1-overexpressing lentivirus infection." (PMID 37949219, 2023).
lupus (1 paper, 2024). "However, a much larger set of TFs contained in the TNF-α signaling gene set appeared among the active TFs in lupus cells; these include FOSL1, KLF6, RELB, BHLHE40, EGR3, and SMAD3." (PMID 39688922, 2024).
lymphoma (1 paper, 2023). A malignant (clonal) proliferation of B- lymphocytes or T- lymphocytes which involves the lymph nodes, bone marrow and/or extranodal sites. "We detected a significant enrichment of c-FOS, FOSL1, FOSL2, c-JUN, and BATF target genes in H3K27ac ChIP–seq peaks upregulated in ITK–SYK+PD-1− lymphoma cells compared to their premalignant ITK–SYK+PD-1+ counterparts." (PMID 37723306, 2023).